SIRT1 (sirtuin 1)
Diseases named in the same sentence as SIRT1 in open-access papers (continued):
Sharing a sentence is not in itself a finding about the gene and the disease.
Sepsis (continued). "Sirt-1/Nrf-2 signaling was a novel therapeutic strategy for sepsis." (PMID 34493741, 2021). "In our study, we first observed enhanced autophagy activity in liver tissues of septic mice treated with DEX, especially at 24 h after sepsis, and then detected an increase of p-AMPK/AMPK and SIRT1 protein levels in the liver of mice with CLP-induced sepsis treated with DEX." (PMID 33981237, 2021). "Moreover, resveratrol demonstrated a capacity to reduce ALI and inflammation in a murine LPS-induced sepsis model through Sirtuin 1 (Sirt1) regulation, an important regulator of inflammation." (PMID 34367380, 2021). "In summary, these data demonstrated that THC could protect the renal tissue from sepsis-induced AKI via the activation of SIRT1 signaling." (PMID 34187277, 2021). "Whereas, whether SIRT1 and SIRT1-related signaling pathways are involved in the curative effects of THC in mitigating sepsis-induced AKI is still unclear." (PMID 34187277, 2021). "SIRT1-regulated deacetylation of HMGB1 inhibits sepsis-induced AKI." (PMID 34250012, 2021). "By establishing animal models and utilizing a variety of experimental methods including molecular biology, this study also elucidated the mechanism of action of LcS + geniposide in ameliorating sepsis via SIRT1 activation by observing the changes in inflammation and oxidative stress in mice." (PMID 34616305, 2021). "However, further experiments were also need to confirm the regulatory axis of OIP5-AS1/miR-128-3p/SIRT1 in sepsis." (PMID 34592882, 2021). "Notwithstanding, whether miR-128-3p modulates sepsis-mediated ALI via targeting SIRT1 remains to be verified." (PMID 34592882, 2021). "One used the highly specific SIRT1 inhibitor, EX-527, in mice 24 h after onset of sepsis." (PMID 34322502, 2021). "Studies have shown that SIRT1 is also closely related to sepsis." (PMID 34721636, 2021). "From this result, we initially proposed that MAR1 reduces the inflammation response in sepsis may be related to the activation of SIRT1/PGC-1α/PPAR-γ axis." (PMID 33557833, 2021). "Our previous studies showed that silent mating-type information regulation 2 homologue-1 (SIRT1, a deacetylase) upregulation could attenuate sepsis-induced acute kidney injury (SAKI)." (PMID 33637691, 2021). "Moreover, melatonin reduced liver injury and cardiac dysfunction after sepsis through SIRT1 upregulation." (PMID 33790896, 2021). "In contrast, sepsis-AKI patients had lowered mRNA expression of Sirtuin 1 (SIRT1), involved in inhibiting oxidative stress and in biogenesis, as compared to control subjects (p < 0.01), while NRF2 important in regulation of antioxidant protein expression was not different between both groups." (PMID 33494815, 2021). "Therefore, we conjectured that OIP5-AS1 modulated the miR-128-3p/SIRT1 axis to guard against ALI incurred by sepsis." (PMID 34592882, 2021). "Because of this, SIRT1 knockout sepsis mice appear to have active NF-κB, STAT3, and extracellular signal-regulated kinase (ERK) 1/2, thus providing the lungs with an unusually strong inflammatory signal by upregulating a range of pro-inflammatory mediators, including IL-ip, IL-6, and TNF-α." (PMID 33693011, 2021). "Sirt-1 was known to protect against sepsis through Sirt-1/Nrf-2 signaling." (PMID 34493741, 2021). "Furthermore, the present study assessed the correlation of SIRT1 with inflammation and disease severity in sepsis patients." (PMID 33263643, 2020).
Sepsis (continued). "In sepsis patients, SIRT1 negatively correlated with serum creatinine (Scr), white blood cells (WBC), C-reactive protein (CRP), acute physiology, and chronic health evaluation II (APACHE II) score, and sequential organ failure assessment (SOFA) score, while it positively correlated with albumin." (PMID 33263643, 2020). "One potential mechanism by which RSV could inhibit HMGB1 release is by preventing HMGB1 nuclear-cytoplasmic translocation through up-regulating SIRT1 in a sepsis-induced liver injury mouse model." (PMID 33139717, 2020). "We found that SIRT1 was associated with ameliorated inflammation and disease severity (reflected by the correlation of SIRT1 with Scr, WBC, CRP, SOFA score, APACHE II score, and albumin) in sepsis patients." (PMID 33263643, 2020). "The Sirt1 activator could also attenuate multiorgan injury in septic mice model, decrease the production of proinflammatory cytokines and reduce inflammasome activation, suggesting that Sirt1 may play an important role in sepsis through the NF-kb pathway." (PMID 32978453, 2020). "We found that pretreatment with melatonin for 3 days before CLP could attenuated sepsis-induced acute lung injury through improvement of ENaC mediated alveolar fluid clearance which maybe through activation of SIRT1/SGK1/Nedd4-2 signaling pathway." (PMID 33362546, 2020). "In conclusion, measurement of serum SIRT1 might assist with the optimization of disease assessment, management strategies, and survival surveillance in sepsis patients." (PMID 33263643, 2020). "Melatonin could attenuate the decrease of αENaC protein expression and SIRT1 protein expression mediated by sepsis." (PMID 33362546, 2020). "In the initial (proinflammatory) phase, which is characterized by a cytokine storm, overproduction of reactive oxygen species (ROS), and metabolic shift, SIRT1 activation shows positive effects, whereas the SIRT1 expression should be inhibited in the later stages of sepsis." (PMID 33414897, 2020). "Therefore, due to the dynamic phases of sepsis, the role of SIRT1 cannot simply be defined as beneficial or detrimental." (PMID 33414897, 2020). "Previous studies have demonstrated that melatonin could protect multiple organs injury during sepsis, and the protective effect of melatonin on organs was mediated by SIRT1, which was an NAD+ dependent deacetylase." (PMID 33362546, 2020). "In the present study, we found that SIRT1 was lower in sepsis patients than that in HCs, and it could distinguish sepsis patients from HCs." (PMID 33263643, 2020). "Sepsis resulted in an increase in Nrf1, Nrf2, and Sirt1 mRNA expression levels." (PMID 32545383, 2020). "Based on the effect of SIRT1 on attenuating inflammation and protecting against multiple organ dysfunction, a hypothesis was proposed that SIRT1 might be related to the occurrence and development of sepsis." (PMID 33263643, 2020). "The ROC curves showed that SIRT1 predicted 28-day mortality risk in sepsis patients, and its predictive value was not inferior to Scr, albumin, WBC, and CRP, while less than SOFA score and APACHE II score." (PMID 33263643, 2020). "SIRT1 has been reported in protecting against sepsis pathogenesis." (PMID 30918470, 2019). "A more direct evidence found that SIRT1 directly attenuated sepsis-induced lung injury." (PMID 30918470, 2019). "The role of SIRT1 alone in sepsis in vitro and in vivo needs to be explored." (PMID 31844680, 2019). "However, little information is available on the relationship between miR-181a-5p and SIRT1 in sepsis in vivo or in vitro." (PMID 31844680, 2019). "All these results indicated that miR-181a-5p negatively regulated the expression of SIRT1, which might affect the progression of sepsis." (PMID 31844680, 2019). "In summary, these results indicated that miR-181a-5p was involved in sepsis through regulating the inflammatory response by targeting SIRT1, suggesting that miR-181a-5p may be a potential target for the treatment of sepsis." (PMID 31844680, 2019).
Sepsis (continued). "SIRT1/2-mediated suppression of inflammation helps to resist the disease in the initial phase and plays a diametrically opposite role in the later phase (immunosuppression phase), which indicates the importance of immune regulation in the treatment of sepsis." (PMID 30533222, 2018). "Subsequent research confirmed that SIRT1 inhibition could strikingly reverse post-acute phase hypoinflammation during the later stage of sepsis." (PMID 30533222, 2018). "In fact, in addition to SIRT1, other molecular-mediated anti-inflammatory responses may share a common contradictory application in sepsis, as a great number of inflammatory mediators exist and accompany all stages of sepsis." (PMID 30533222, 2018). "Because SIRT1 levels were altered during sepsis we sought to determine whether changes in SIRT1 levels affect the expression of pro-inflammatory cytokines." (PMID 29867921, 2018). "Some scholars have suggested that SIRT1 plays different roles in the different stages of sepsis." (PMID 30533222, 2018). "Considering inflammation exists at the center of the development of metabolic, immunologic, and infectious diseases, we believe that SIRT1 and its family members may play vital roles in the pathogenesis of sepsis." (PMID 30533222, 2018). "Subsequent studies sought to explore the exact mechanism of SIRT1 in sepsis." (PMID 30533222, 2018). "Numerous studies have shown that SIRT1 can reduce inflammatory response after sepsis." (PMID 30533222, 2018). "In addition to SIRT1, other members also play different roles during sepsis, plus their respective targets are varied." (PMID 30533222, 2018). "It has been reported previously that, SIRT1 exerts protective effects in sepsis." (PMID 30186119, 2018). "Therefore, SIRT1, as a key target in this important inflammatory signaling pathway, will also be a crucial target in the treatment of brain dysfunction induced by sepsis." (PMID 30186119, 2018). "Thus, in inflammation and sepsis, the SIRT1 level was decreased and this led to severe damage, whereas SIRT1 activation protected against inflammation and sepsis." (PMID 29867921, 2018). "Similarly, we observed decreased survival in obese mice with SIRT1 inhibition during hypo-inflammation of sepsis in obese mice." (PMID 30216989, 2018). "The aim of this study was to determine whether BML-111 can improve neuroinflammation and cognitive impairment in sepsis via the SIRT1/NF-κB signaling pathway." (PMID 30186119, 2018). "After verifying that SIRT1 was downregulated in LPS-induced sepsis, we tested whether Notch signaling was altered during this process." (PMID 29867921, 2018). "If this coupling occurs during sepsis, it would suggest that SIRT1 targeting of the global immune dysregulated state of innate and adaptive immune cells might inform a unified sepsis treatment approach for immune enhancement treatment of human sepsis." (PMID 30069485, 2018). "This implies that SIRT1-mediated epigenetic coordination might be a critical target in the later stages of sepsis." (PMID 30533222, 2018). "Whether SIRT1 inhibition during sepsis treatment concomitantly reverses innate and T cell antigen-specific immune tolerance is unknown." (PMID 30069485, 2018). "In the early stages of toll-like receptor 4- (TLR4-) mediated sepsis, SIRT1 rapidly accumulated at TNF-α and IL-1β promoter regions and deacetylated the RelA/p65 lysine 310 site and nuclear histone H4 lysine 16 sites, ultimately promoting NF-κB transcription termination." (PMID 30533222, 2018). "Hence, the role of SIRT1 in the pathogenesis of sepsis cannot be simply defined as beneficial or detrimental but should be viewed dynamically." (PMID 30533222, 2018). "In addition, resveratrol (a SIRT1 agonist) treatment suppressed the over-expression of pro-inflammatory molecules and decreased acute lung injury in a sepsis mouse model induced by LPS via activation of SIRT1 and elimination of the oxidative stress." (PMID 29997508, 2018).
Sepsis (continued). "It has been found that SIRT1 activation could ameliorate sepsis-induced inflammatory response and protect kidney from acute injury." (PMID 28852469, 2017). "The in vivo results clearly demonstrated a significant reduction in the bacterial load in different organs and in the inflammatory markers such as COX-2 and NF-κB via activation of SIRT1 in mice treated with imipenem, a choice of antibiotic for polymicrobial sepsis treatment." (PMID 28533769, 2017). "Furthermore, we elucidated that salidroside prevented the HMGB1 nucleocytoplasmic translocation and HMGB1 release during sepsis via a SIRT1-mediated signaling pathway." (PMID 28931916, 2017). "In this study, we used a potential SIRT1 activator, resveratrol, for treatment of sepsis." (PMID 28003866, 2016). "In the genes differentially expressed between SRS groups, there was evidence of enrichment for eQTL (χ2 p<0·0001), including for genes previously implicated in the pathogenesis of sepsis and its treatment, such as IL18RAP, CCR1, CCR3, and SIRT1 (appendix 1 pp 17–18 and appendix 2)." (PMID 26917434, 2016). "This study outlines an important role for SIRT1 in the reversal of AKI following sepsis." (PMID 28003866, 2016). "However, the role of SIRT1 in sepsis is rarely studied and its exact mechanism is yet to be determined." (PMID 28003866, 2016). "We first studied whether there was a difference in SIRT-1 expression in small intestinal tissue during hyper-inflammatory phase (6 hours) vs. hypo-inflammatory phase (24 hours) of sepsis." (PMID 27500833, 2016). "To further investigate the potential differences in ob/ob vs. WT sepsis, we tested whether treatment with SIRT1-specific inhibitor EX-527 improved 7- day survival in ob/ob mice." (PMID 27500833, 2016). "We have studied the role of SIRT1 in rodent sepsis with the focus on microvasculature." (PMID 26904696, 2016). "In addition, we found that IFN-β inhibits LPS-induced secretion of proinflammatory cytokines and protects against endotoxemia and sepsis via SIRT1 upregulation." (PMID 24573134, 2014). "Our results also suggest that IFN-β and its downstream target, SIRT1, have important roles in anti-inflammatory responses and may be potential targets for treatment of patients with sepsis." (PMID 24573134, 2014). "Accordingly, we speculated that S1P alleviates sepsis by inducing SIRT1 expression in macrophages." (PMID 40470379, 2025). "Sustained activators of S1P1 and SIRT1 may be important targets for sepsis therapeutics." (PMID 40470379, 2025). "Furthermore, IFN‐β, which induces SIRT1, offers protection against sepsis." (PMID 40470379, 2025). "It has been previously shown that Sirt1 is downregulated in macrophages in preclinical models of sepsis and may play a role in orchestrating innate immune activation, particularly through the activation of NF-κB and the subsequent production of pro-inflammatory cytokines such as IL-6 and TNF-α." (PMID 41096578, 2025). "Furthermore, in a mouse model of sepsis, the SIRT1 activator resveratrol can alleviate inflammatory responses and organ damage by upregulating IL-10 expression, suggesting that SIRT1-induced IL-10 can significantly antagonize the inflammatorycascade amplification mediated by NF-κB." (PMID 38745862, 2024). "By enhancing the SIRT1-mediated deacetylation of HMGB1, CGK012 may mitigate the damaging effects of HMGB1 on the vascular barrier, highlighting its therapeutic potential in pathological vascular inflammation associated with conditions such as sepsis." (PMID 38474222, 2024). "Consequently, the SIRT1-regulated NOX4-Nrf2 axis may represent a crucial target for echinacoside in the treatment of sepsis-induced acute lung injury." (PMID 38001778, 2023). "Moreover, overexpression of SIRT1 was reported to inhibit LPS-induced inflammatory gene expression, and resveratrol, an activator of SIRT1, has been demonstrated to attenuate sepsis-induced cardiac, liver, kidney, and lung injuries by inhibiting oxidative stress." (PMID 38001778, 2023).
Sepsis (continued). "On the contrary, some studies have shown that SIRT1 may play an adverse role in sepsis." (PMID 37475042, 2023). "We further verified whether the regulation of NAD+ on sepsis‐related AKI depends on SIRT1." (PMID 35137552, 2022). "Therefore, this study is dedicated to probing into the effect of miR-197 on sepsis-induced cardiomyocyte injury as well as elucidating its relationship with SIRT1 in order to provide new therapeutic clues for maintaining cardiac function in septic myocardial inflammation." (PMID 35223094, 2022). "However, it is poorly understood whether the effect of SIRT1 on sepsis-driven myocarditis can be regulated by miR-197." (PMID 35223094, 2022). "Consequently, these data confirmed that THC could protect the renal tissue from sepsis-induced AKI via the activation of SIRT1 and its related downstream signaling." (PMID 34187277, 2021). "Deacetylase Sirtuin1 (Sirt1) dependent pathway might play a pivotal role in sepsis-AKI." (PMID 34926535, 2021). "Hence, we explored whether miR-9-5p and SIRT1 participate in the protective role of EVs shuttled TUG1 in sepsis." (PMID 34743197, 2021). "Furthermore, we divided sepsis patients into SIRT1 high group and SIRT1 low group based on their median SIRT1 level, and observed that the accumulating mortality was attenuated in sepsis patients with SIRT1 high expression compared to sepsis patients with SIRT1 low expression (P=0.006)." (PMID 33263643, 2020). "In our study, although SIRT1 exhibited a slightly inferior predictive value for 28-day mortality risk compared with APACHE II score and SOFA score, it still had a clinical significance as a rapidly measurable prognostic biomarker in sepsis patients in the clinical setting." (PMID 33263643, 2020). "In the present study, we disclosed that SIRT1 was decreased in 28-day non-survivors compared with 28-day survivors, and it could predict 28-day mortality risk in sepsis patients by the ROC curve." (PMID 33263643, 2020). "To conclude, SIRT1 distinguished sepsis patients from HCs, and it correlated with lower disease severity and better prognosis in sepsis patients, which offers new perspectives for facilitating management strategies and survival surveillance of sepsis in clinical practice." (PMID 33263643, 2020). "Moreover, a recent publication demonstrated that SIRT1 could reverse sepsis-induced myocardial injury via anti-inflammation and relieving ER stress." (PMID 30918470, 2019). "Therefore, we hypothesized that ginsenoside Rg1 might ameliorate sepsis-induced cell ER stress and apoptosis via upregulating SIRT1, eventually protecting against lung inflammation or injury." (PMID 30918470, 2019). "However, SIRT1 inhibition during early sepsis decreased survival in lean mice." (PMID 30216989, 2018). "Interestingly, SIRT1 protein levels decreased during the early/hyper-inflammation of sepsis." (PMID 30216989, 2018). "Besides, the oxidation of cysteine on SIRT6 and SIRT2 as well as the nitrosylation of SIRT1 could decrease their expression, respectively, during sepsis." (PMID 30533222, 2018). "Using THP-1 pre-monocytic cells with LPS stimulation and peripheral blood mononuclear cells from sepsis patients, we showed that during the hypo-inflammatory phase of sepsis, increased fatty acid oxidation with decreased glycolysis occurs with increased SIRT1 levels." (PMID 30216989, 2018). "However, the role of the SIRT1/NF-κB signaling pathway in the protective effects of BML-111 against sepsis-induced neuroinflammation and cognitive impairment remains unclear." (PMID 30186119, 2018). "However, it remains unknown whether there is a relationship between Sirt1 and β-catenin in a sepsis model." (PMID 29209448, 2017). "Moreover, sepsis decreased the SIRT1 protein expression in the lungs of CLP septic mice." (PMID 28931916, 2017). "Therefore, we hypothesized that SIRT1 signaling pathway might be involved in the therapeutic effect of salidroside on sepsis-induced acute lung injury." (PMID 28931916, 2017).